LEP (leptin)
Diseases named in the same sentence as LEP in open-access papers (continued):
Sharing a sentence is not in itself a finding about the gene and the disease.
osteoarthritis (continued). "In RA, circulating and synovial leptin levels were reported to be elevated compared to those observed in healthy controls or osteoarthritis patients." (PMID 21234350, 2010). "The significant relationship between adiposity, leptin, and osteoarthritis in high-fat-fed mice is consistent with previous reports of the proinflammatory actions of leptin in cartilage." (PMID 20604941, 2010). "A significant level of three adipokines (leptin, adiponectin, resistin) has previously been found in synovial fluid of RA and osteoarthritis patients." (PMID 20017992, 2009). "Several of these target genes such as ADAMTS5, GDF5 and LEP have been previously correlated with osteoarthritis." (PMID 19011694, 2008). "Leptin and interleukin-1 beta (IL-1β) levels among different groups categorized by age, body mass index (BMI), number of involved joints, and disease duration in osteoarthritis patients." (PMID 37703108, 2023). "Therefore, we have tried to explore the effects on apoptosis and autophagy in chondrocytes in the pathogenesis of osteoarthritis due to leptin." (PMID 35035830, 2022). "Another analysis involving 6408 participants also indicated that leptin levels but not adiponectin were associated with OA and partially mediated the association between adiposity and osteoarthritis." (PMID 36615120, 2022). "There are three types of autophagy, including macroautophagy, microautophagy, and CMA; similar to the results of our study, leptin is an inhibitor of autophagy to promote apoptosis of chondrocytes through PI3K/AKT signal pathway during osteoarthritis pathogenesis." (PMID 34717752, 2021). "In our study, LEP promoter methylation levels were higher in obese individuals with osteoarthritis." (PMID 31878053, 2019). "Most studies have demonstrated that serum leptin levels in people with osteoarthritis are high." (PMID 31878053, 2019). "LEP is one of the main regulators of osteoarthritis pathogenesis." (PMID 31878053, 2019). "Furthermore, osteoarthritis osteoblasts produce high levels of leptin (Mutabaruka, Aoulad Aissa, Delalandre, Lavigne, & Lajeunesse, 2010)." (PMID 28425564, 2017). "High leptin levels in osteoarthritis might play a role in increased levels of bone markers, such as alkaline phosphatase and osteocalcin observed in osteoblasts." (PMID 28425564, 2017). "Lastly, the CSF leptin levels reported herein are similar to those previously observed in subjects without underlying osteoarthritis, arguing against osteoarthritis-induced alterations in leptin levels." (PMID 25835291, 2015). "For instance, leptin and chemerin, positively correlated with the severity of osteoarthritis." (PMID 25853553, 2015). "Leptin is abundantly expressed in osteoarthritis (OA) cartilage and synovium." (PMID 24086566, 2013). "Leptin has been suspected to contribute to the development of osteoarthritis (OA)." (PMID 22651805, 2012). "Given the pleiotropic effects of leptin in regulating appetite, skeletal metabolism, fertility, and many other physiologic functions, however, targeting leptin directly may prove overly complex as an osteoarthritis therapy." (PMID 20604941, 2010). "Osteoarthritis increases the expression of leptin and leptin receptors in chondrocytes, suggesting that physiologic levels of leptin may mediate the production of inflammatory mediators in osteoarthritic but not normal tissue." (PMID 20604941, 2010). "For example, recent studies have shown that mice deficient in leptin or the leptin receptor undergo extreme weight gain but exhibit no changes in osteoarthritis." (PMID 20604941, 2010). "Increasing evidence support the regulatory role of leptin in osteoarthritis (OA)." (PMID 20534145, 2010). "Thus, in patients with inflammatory synovitis or osteoarthritis, there is a unique microenvironment in the cartilage characterized by elevated levels of both leptin and IL-1, due not only to local production but also to systemic increase." (PMID 15899045, 2005).
osteoarthritis (continued). "Interestingly, in patients with osteoarthritis leptin is present in synovial fluid and is expressed by articular chondrocytes, and normal human chondrocytes express the functional Ob-Rb leptin receptor isoform." (PMID 15899045, 2005). "However, it remains unclear whether serum and SF leptin have distinct roles in the mechanisms involved in osteoarthritis." (PMID 39409194, 2024). "Patients with degenerative joint disease, when exposed to leptin, respond by producing proinflammatory cytokines such as IL-8, IL-6, and TNF-alpha, which may intensify the catabolism of proteoglycans, increase the expression of metalloproteinases (MMP), and thereby stimulate cartilage degradation." (PMID 38203376, 2023). "High levels of LEP expressions promote the synthesis and expression of nitric oxide, matrix metalloprotease-9, and matrix metalloprotease-13 in chondrocytes, thereby affecting their functions which could finally result in osteoarthritis." (PMID 31878053, 2019). "Our findings suggest that LEP methylation might be involved in the pathogenesis of osteoarthritis." (PMID 31878053, 2019). "Other in vitro studies indicate that leptin alone or in the presence of IL-1 induces COX2 and PGE2 by mitogen-activated protein kinase (MAPK) pathway activation in osteoarthritis cartilage." (PMID 32820432, 2021). "Our objective was to evaluate the relationship between the preoperative serum leptin levels and postoperative VTE incidence in osteoarthritis (OA) patients who underwent total knee arthroplasty (TKA) at our institute." (PMID 29794796, 2018). "Similarly, leptin alone and by co-stimulation with IL-1ß enhanced the production of MMP-1, MMP-3, and MMP-13 in knee cartilage from patients with osteoarthritis." (PMID 33396484, 2020). "The mean LEP promoter methylation level in individuals with osteoarthritis was 0.5509 ± 0.00437 and 0.5375 ± 0.00101 in those without osteoarthritis." (PMID 31878053, 2019). "We identified that PPARA, BMP7, IL1B, LEP, ITGA5 and SREBP1 protein levels in osteoarthritic chondrocytes were highly correlated with BMI, suggesting the potential role of metabolic-related proteins in the development of osteoarthritis." (PMID 19011694, 2008). "However, a multiplicative effect was observed for the interaction between P3NP and serum level of leptin (− 0.04 ± 0.01, p value < 0.001) regardless of age, sex, fat mass, and osteoarthritis." (PMID 37532926, 2024). "Upregulation of Loxl3 with leptin treatment of primary chondrocytes from affected rat knees with increased apoptosis and concomitant suppression of autophagy corroborated LOXL3 involvement in osteoarthritis and point to it as a potential therapeutic target in this disease." (PMID 31340433, 2019). "Here, we have investigated the relationship between gender, leptin, body mass index (BMI) and levels of the endocannabinoids anandamide (AEA) and 2-arachidonoylglycerol (2-AG) in the serum and cerebrospinal fluid (CSF) of primarily overweight to obese patients with osteoarthritis." (PMID 25835291, 2015). "Physiologic levels of leptin do not alter extracellular matrix homeostasis in healthy cartilage, suggesting that leptin may be a secondary mediator of osteoarthritis pathogenesis." (PMID 20604941, 2010). "Physiologic levels of leptin do not alter extracellular matrix homeostasis in healthy cartilage, suggesting that leptin may be a secondary mediator of cartilage degeneration in osteoarthritis." (PMID 20604941, 2010). "In a study from 2007 where leptin levels were analysed in 30 patients with RA and 30 patients in a control group with osteoarthritis, the authors could not find any difference in leptin levels between groups, possibly because both these groups commonly have chronic pain and raised leptin levels?" (PMID 39716315, 2024). "The pathogenesis of osteoarthritis (OA) is not clear; leptin may be related to its pathogenesis." (PMID 29620639, 2018).
myocardial infarction (69 papers, 2005 to 2026). Gross necrosis of the myocardium, as a result of interruption of the blood supply to the area, as in coronary thrombosis. "L. rhamnosus GR-1 and L. plantarum 299v reduce the risk of myocardial infarction, improve ventricular function, and reduce the infarct size by decreasing the levels of leptin in rats." (PMID 33897683, 2021). "It is crucial to understand the mechanism which drive these changes in leptin levels because leptin has been reported to be related with an increased risk of myocardial infarction, hemorrhagic stroke, abnormal fibrinolysis in men and postmenopausal women." (PMID 34671315, 2021). "Leptin is also elevated in cardiovascular events such as acute myocardial infarction (AMI) and hence is considered as modifiable risk factors for AMI." (PMID 33489600, 2020). "Adiponectin and leptin are adipose tissue-derived peptides that are associated with myocardial infarction in the general population." (PMID 30356397, 2018). "Serum leptin levels are reported to be associated with various cardiovascular risks, including stroke, chronic heart failure, acute myocardial infarction, coronary heart disease, and left cardiac hypertrophy." (PMID 25762868, 2015). "In the cardiovascular system, hyperleptinemia has been linked to left ventricular mass in severe obese patients, elevated serum leptin concentrations are found in patients with congestive heart failure, and leptin has been identified as a risk factor for myocardial infarction." (PMID 23270329, 2012). "We therefore focused on Chennai based population with an attempt to understand if serum leptin concentration is associated with myocardial infarction, with particular emphasis on the relationship between serum leptin and inflammatory markers such as IL-6 and CRP in AMI condition." (PMID 22891684, 2012). "For example, epidemiological studies showed that increased plasma leptin levels correlate positively with adverse cardiovascular outcomes, such as myocardial infarction (MI) and congestive heart failure (HF)." (PMID 39612121, 2024). "Chronic activation of the brain leptin-melanocortin pathway improves cardiac function and metabolism following myocardial infarction." (PMID 39612121, 2024). "In the context of myocardial infarction, leptin was shown to be cardioprotective by direct and indirect effects, for example by protection of cardiomyocytes from apoptosis and by improvement of cardiac substrate oxidation." (PMID 36388122, 2022). "Administration of Lactobacillus Plantarum suppresses circulating leptin, and improves left ventricular function, ultimately leading to decreased myocardial infarct size and post ischemic adverse chamber remodeling." (PMID 35806159, 2022). "It has been reported that plasma leptin and visfatin levels were increased in patients with myocardial infarction or other cardiovascular diseases." (PMID 34422210, 2021). "In those studies, the use of broad-spectrum antibiotics was shown to affect levels of leptin and analytes produced during aromatic amino acid catabolism (e.g., phenylalanine, tryptophan, tyrosine), and subsequently reduce myocardial infarct size." (PMID 32060329, 2020). "CK-MB, a biomarker for the myocardial infarction, is positively correlated with ghrelin and negatively correlated with leptin." (PMID 30674322, 2019). "Here, we evaluated inflammation and leptin to adiponectin ratio in pericoronary fat from patients subjected to coronary artery bypass grafting (CABG) for acute myocardial infarction (AMI)." (PMID 31570103, 2019). "Clinical studies showed a positive correlation between leptin levels and development of macrovascular complication of obesity such as myocardial infarction and cerebral stroke." (PMID 28286779, 2017). "Patients with acute myocardial infarction have been reported to have a trend for an increased serum leptin level with an increasing number of diseased vessels." (PMID 27151106, 2016).
myocardial infarction (continued). "In our previous study, vancomycin decreased circulating leptin levels, resulted in smaller myocardial infarcts and improved recovery of post ischemic mechanical function as compared with untreated controls." (PMID 27505423, 2016). "The relationships of time-domains of HRV, markers of overall autonomic function, with plasma leptin are only shown in male school teachers and males with acute myocardial infarction." (PMID 26338087, 2015). "One of the two leptin studies demonstrated elevated leptin in PTSD patients after myocardial infarction and another in earthquake survivors with subsyndromal PTSD." (PMID 25926799, 2015). "The current study demonstrates elevation of serum leptin levels in the acute phase of myocardial infarction and it peaks at 36 hours after admission (doubled)." (PMID 22642879, 2012). "Notably, administration of broad‐spectrum antibiotics in rats has been shown to affect leptin concentrations and the metabolites produced during the breakdown of aromatic amino acids, thereby reducing myocardial infarction severity." (PMID 39568773, 2024). "Interestingly, the results of Nagoya Acute Myocardial Infarction Study shown, that decreased leptin level is connected with a high incidence of adverse events in patients after acute MI17." (PMID 35821400, 2022). "Leptin signalling has been shown to ameliorate cardiac dysfunction and remodelling four weeks after myocardial infarction by increasing STAT3 phosphorylation in calorie-restricted lean and obese ob/ob mice as well as in tamoxifen-inducible leptin receptor knockout mice." (PMID 30424579, 2018). "In this study, the broad-spectrum antibiotic vancomycin altered the abundance of individual groups of intestinal microbiota and decreased circulating leptin levels, resulting in smaller myocardial infarcts and improved recovery of post ischemic mechanical function." (PMID 27505423, 2016). "Dahl S rats fed the commercially available probiotic product Goodbelly, which contains the leptin-suppressing bacteria Lactobacillus plantarum 299v, resulted in decreased circulating leptin levels, smaller myocardial infarcts, and greater recovery of postischemic mechanical function." (PMID 25849657, 2015). "Indeed, elevated serum LEP levels were found in PTSD patients suffering from depressive symptoms caused by earthquakes and myocardial infarctions." (PMID 25295026, 2014). "In a previous study we suggested that TNF alpha may represent a modulator of leptin action in the hypothalamus, such finding may have implication in the setting of acute myocardial infarction." (PMID 22642879, 2012). "A preliminary study in a small number of patients suggested that leptin levels might increase with acute myocardial infarction." (PMID 22642879, 2012). "When rats were fed fruit juice containing L. plantarum 299v and B. lactis Bi-07, the study results showed that this probiotic supplementation decreased circulating leptin levels and reduced myocardial infarction to the same extent as with the use of vancomycin." (PMID 23049548, 2012). "Patients with myocardial infarction (MI) have increased circulating levels of leptin, which correlates with pro-inflammatory markers, suggesting that leptin is associated with the inflammatory response produced during an AMI." (PMID 33081064, 2020). "Our study indicates leptin levels might be a predictor for future myocardial infarction." (PMID 33489600, 2020). "Pioneering studies by our group confirmed that hypoxia preconditioning could enhance the therapeutic efficiency of MSCs in rodent myocardial infarction (MI) models, and we further proposed that leptin was an obligatory intermediate in the anti-apoptotic properties of MSCs6,7." (PMID 29748581, 2018).
myocardial infarction (continued). "In addition, the leptin suppressing probiotic bacterium, Lactobacillus plantarum 299v (live microorganism beneficial to its host), that lives in the intestines, also resulted in decreased leptin levels, smaller myocardial infarcts and greater recovery of post-ischemic mechanical function." (PMID 27505423, 2016). "It is postulated that LEP may be involved in the body's response to stress; for example, LEP can play a role of acute phase protein, adapting the cellular metabolism to stress, e.g., in myocardial infarction." (PMID 26389928, 2015). "Evidence suggests that leptin can stimulate inflammatory response by activating TNF-α via p38 and JNK MAPK pathway and these inflammatory markers may be associated with the risk of recurrent myocardial infarction and death." (PMID 25762868, 2015). "Experimental work demonstrates that activation of hypothalamic leptin and melanocortin-4 receptor (MC4R) pathways confers cardioprotection after myocardial infarction, even in the presence of peripheral leptin resistance." (PMID 41596265, 2026). "Importantly, it has been demonstrated that chronic intracerebroventricular (ICV) leptin infusion protects the heart from adverse remodeling and cardiac contractile dysfunction after myocardial infarction (MI)." (PMID 39199415, 2024). "Interestingly, the αMUPA female mice that were subjected to myocardial infarction (MI) showed increased fractional shortening, decreased infarction duration, inflammatory response, cardiac ageing, and elevated serum leptin levels." (PMID 37887341, 2023). "Previous study on serum leptin, IL-6 and hs-CRP levels have been conducted in acute myocardial infarction (AMI) patients from south India (Chennai)." (PMID 30001365, 2018). "Moreover, chronic leptin infusion increased cardiac ANP expression after myocardial infarction (MI) in mice, whereas neutralizing LepR antibodies abrogated the hypertrophy of the surviving myocardium after coronary artery ligation in rats." (PMID 23841921, 2013). "Serum levels of leptin, IL-6 and CRP were evaluated for 93 Acute Myocardial Infarction (AMI) patients and 102 control subjects." (PMID 22891684, 2012). "Importantly, eating is a well-established trigger for myocardial infarction, due to increased SNA, suggesting that the interplay between leptin and the baroreflex is significant." (PMID 32538782, 2020). "In another study by Yan GT which explored the correlation between leptin and troponin t, concluded that the level of leptin serum and troponin in patients with acute myocardial infarction and coronary atherosclerosis none significantly increased when this increase not significant." (PMID 25914798, 2015). "The aims of the current study were to evaluate serial levels of serum leptin among patients presenting with acute myocardial infarction (AMI) and whether there is a correlation between leptin and coronary reperfusion as well as with angiographic and echocardiographic data." (PMID 22642879, 2012). "Notably, pericoronary fat could over-express the sodium-glucose cotransporter 2 (SGLT2) and leptin, along with decreased sirtuin 6 (SIRT6) expression in PDM vs. normoglycemic (NG) patients undergoing coronary artery bypass grafting (CABG) for acute myocardial infarction (AMI)." (PMID 34440108, 2021). "Studies from our laboratory showed that CNS LepR activation, without raising plasma leptin levels, has remarkable beneficial effects on cardiac metabolism and function that protect the heart during pathological conditions, including heart failure (HF) induced by myocardial infarction (MI)." (PMID 39612121, 2024).